RN7SKP86 (RN7SK pseudogene 86)
Gene: Miscellaneous RNA gene on chromosome 7 (103,484,208 to 103,484,539, reverse strand). Ensembl gene ENSG00000222386.
Homologues: Orthologues: chimpanzee 7SK (98% identical). Paralogues in human: RN7SKP180 (72% identical), RN7SKP124 (72% identical), 7SK (71% identical), RN7SKP133 (71% identical), RN7SKP203 (70% identical), RN7SKP77 (70% identical), RN7SKP9 (70% identical), RN7SKP146 (70% identical), RN7SKP217 (70% identical), RN7SKP71 (70% identical), RN7SKP184 (70% identical), RN7SKP189 (69% identical), and 284 more.